GAL3ST3 (galactose-3-O-sulfotransferase 3)
Description:
Catalyzes the transfer of a sulfate group from 3'-phosphoadenylyl sulfate (PAPS) to the C-3 hydroxyl group of terminal non-reducing beta-1,4-linked galactose residues in both N-glycans and O-glycans. It acts efficiently on type 2 chains (Gal-beta-1,4-GlcNAc-R) found in N-glycans and core 2-branched O-glycans (Gal-beta-1,4-GlcNAc-beta-1,6(Gal-beta-1,3)GalNAc-R). In contrast, it shows poor activity on type 1 chains (Gal-beta-1,3-GlcNAc-R) and intermediate activity on core 1 structures (Gal-beta-1,3-GalNAc-R). Participates in the glycoconjugates sulfation namely the 3'-sulfated Lewis X epitope (Gal-beta-1,4(Fuc-alpha-1,3)GlcNAc), by sulfating N-acetyllactosamine (Gal-beta-1,4-GlcNAc) at the 3' position; then the resulting modification is fucosylated by FUT5.
Synonyms: Gal3ST-3; GAL3ST2
Tractability: Antibody: UniProt predicts a signal peptide or a membrane-spanning region. PROTAC: its protein half-life has been measured.
Gene: Protein-coding gene on chromosome 11 (66,040,748 to 66,049,502, reverse strand). Ensembl gene ENSG00000175229.
Subcellular location: Golgi apparatus, Golgi stack membrane
Gene Ontology:
Molecular function: galactose 3-O-sulfotransferase activity; protein binding; 3'-phosphoadenosine 5'-phosphosulfate binding; carbohydrate binding; proteoglycan sulfotransferase activity; galactosylceramide sulfotransferase activity
Biological process: monosaccharide metabolic process; oligosaccharide metabolic process; poly-N-acetyllactosamine metabolic process; proteoglycan biosynthetic process; sulfur compound metabolic process; glycolipid biosynthetic process
Cellular component: membrane; Golgi cisterna membrane
Genetic constraint (gnomAD): Loss-of-function variants: 25 observed, 20.56 expected, observed/expected ratio (o/e) 1.22, 90% interval 0.88 to 1.69. The synonymous counts are far from expectation, so gnomAD's model fits this gene poorly and the ratio says little. Missense variants: 739 observed, 599.57 expected, observed/expected ratio (o/e) 1.23, 90% interval 1.16 to 1.31. Synonymous variants: 355 observed, 280.62 expected, observed/expected ratio (o/e) 1.26, 90% interval 1.16 to 1.38.
Homologues: Orthologues: chimpanzee GAL3ST3 (99% identical), macaque GAL3ST3 (99% identical), rabbit GAL3ST3 (97% identical), dog GAL3ST3 (96% identical), pig GAL3ST3 (95% identical), mouse Gal3st3 (95% identical), rat Gal3st3 (95% identical), guinea pig GAL3ST3 (81% identical), zebrafish gal3st3 (55% identical). Paralogues in human: GAL3ST2 (34% identical), GAL3ST1 (33% identical), GAL3ST4 (31% identical).